TUBA3C (tubulin alpha 3c)
Description:
Tubulin is the major constituent of microtubules, a cylinder consisting of laterally associated linear protofilaments composed of alpha- and beta-tubulin heterodimers. Microtubules grow by the addition of GTP-tubulin dimers to the microtubule end, where a stabilizing cap forms. Below the cap, tubulin dimers are in GDP-bound state, owing to GTPase activity of alpha-tubulin.
Synonyms: TUBA2; bA408E5.3
Tractability: Small molecule: an approved drug acts on it; a high-quality ligand is known; it belongs to a druggable protein family. PROTAC: ubiquitination databases record sites on it; a small molecule that binds it is known. Other modalities: an approved drug acts on it.
Gene: Protein-coding gene on chromosome 13 (19,173,772 to 19,181,824, reverse strand). Ensembl gene ENSG00000198033.
Subcellular location: Cytoplasm, cytoskeleton
Subcellular location (Human Protein Atlas): Microtubules; Primary cilium
Pathways (Reactome):
Cell Cycle: EML4 and NUDC in mitotic spindle formation; Mitotic Prometaphase; Recruitment of NuMA to mitotic centrosomes; Resolution of Sister Chromatid Cohesion; Sealing of the nuclear envelope (NE) by ESCRT-III; Separation of Sister Chromatids; The role of GTSE1 in G2/M progression after G2 checkpoint
Vesicle-mediated transport: COPI-dependent Golgi-to-ER retrograde traffic; COPI-independent Golgi-to-ER retrograde traffic; COPI-mediated anterograde transport; Gap junction assembly; Microtubule-dependent trafficking of connexons from Golgi to the plasma membrane; Translocation of SLC2A4 (GLUT4) to the plasma membrane
Metabolism of proteins: Carboxyterminal post-translational modifications of tubulin; Formation of tubulin folding intermediates by CCT/TriC; Post-chaperonin tubulin folding pathway; Prefoldin mediated transfer of substrate to CCT/TriC
Signal Transduction: Hedgehog 'off' state; RHO GTPases Activate Formins; RHO GTPases activate IQGAPs
Immune System: MHC class II antigen presentation; PKR-mediated signaling
Neuronal System: Activation of AMPK downstream of NMDARs; Assembly and cell surface presentation of NMDA receptors
Organelle biogenesis and maintenance: Cargo trafficking to the periciliary membrane; Intraflagellar transport
Autophagy: Aggrephagy
Cellular responses to stimuli: HSP90 chaperone cycle for steroid hormone receptors (SHR) in the presence of ligand
Developmental Biology: Recycling pathway of L1
Disease: HCMV Early Events
Hemostasis: Kinesins
Gene Ontology:
Molecular function: GTP binding; GTPase activity; structural constituent of cytoskeleton
Biological process: mitotic cell cycle; cytoskeleton organization; microtubule-based process
Cellular component: cilium; microtubule cytoskeleton; nucleus; cytoskeleton; microtubule
Genetic constraint (gnomAD): Loss-of-function variants: 25 observed, 37.77 expected, observed/expected ratio (o/e) 0.66, 90% interval 0.48 to 0.92. The upper end of that interval is the gene's LOEUF score, 0.92, which puts it in group 3 of 6, group 1 being the genes least tolerant of losing a copy. Missense variants: 402 observed, 632.56 expected, observed/expected ratio (o/e) 0.64, 90% interval 0.58 to 0.69. Synonymous variants: 269 observed, 255.99 expected, observed/expected ratio (o/e) 1.05, 90% interval 0.95 to 1.16.
Homologues: Orthologues: chimpanzee TUBA3C (100% identical), mouse Tuba3b (100% identical), rat Tuba3b (100% identical), guinea pig TUBA3C (99% identical), rabbit TUBA3C (99% identical), Drosophila melanogaster alphaTub84B (98% identical), Drosophila melanogaster alphaTub84D (97% identical), zebrafish tuba7l (95% identical), tropical clawed frog tuba1cl (64% identical). Paralogues in human: TUBA3D (100% identical), TUBA3E (99% identical), TUBA1A (98% identical), TUBA1B (97% identical), TUBA1C (96% identical), TUBA4A (94% identical), TUBA8 (91% identical), TUBAL3 (72% identical), TUBB4B (42% identical), TUBB4A (42% identical), TUBB (42% identical), TUBB3 (42% identical), and 11 more.
Diseases named in the same sentence as TUBA3C in open-access papers:
TUBA3C is named in the same sentence as 8 diseases in open-access papers, as found by Europe PMC text mining. Sharing a sentence is not in itself a finding about the gene and the disease.
cancer (1 paper, 2017). A tumor composed of atypical neoplastic, often pleomorphic cells that invade other tissues.
TUBA3C also shares sentences with these, for which no sentence is quoted: arrhythmogenic right ventricular dysplasia/cardiomyopathy (1 paper); cardiovascular disorder (1); idiopathic ventricular fibrillation (1); Infertility (1); Naxos disease (1); varicocele (1); ventricular septal defect (1).